GRAMD1A (GRAM domain containing 1A)
Description:
Cholesterol transporter that mediates non-vesicular transport of cholesterol from the plasma membrane (PM) to the endoplasmic reticulum (ER) (By similarity). Contains unique domains for binding cholesterol and the PM, thereby serving as a molecular bridge for the transfer of cholesterol from the PM to the ER (By similarity). Plays a crucial role in cholesterol homeostasis and has the unique ability to localize to the PM based on the level of membrane cholesterol (By similarity). In lipid-poor conditions localizes to the ER membrane and in response to excess cholesterol in the PM is recruited to the endoplasmic reticulum-plasma membrane contact sites (EPCS) which is mediated by the GRAM domain (By similarity). At the EPCS, the sterol-binding VASt/ASTER domain binds to the cholesterol in the PM and facilitates its transfer from the PM to ER (By similarity). May play a role in tumor progression (By similarity). Plays a role in autophagy regulation and is required for biogenesis of the autophagosome. This function in autophagy requires its cholesterol-transfer activity.
Synonyms: KIAA1533; LAMa; FLJ90346
Tractability: Antibody: UniProt places it where antibodies can reach, with high confidence; its Gene Ontology location is reachable by antibodies, with high confidence; UniProt predicts a signal peptide or a membrane-spanning region; the Human Protein Atlas places it where antibodies can reach. PROTAC: ubiquitination databases record sites on it; its protein half-life has been measured.
Gene: Protein-coding gene on chromosome 19 (34,994,784 to 35,026,471, forward strand). Ensembl gene ENSG00000089351.
Subcellular location: Endoplasmic reticulum membrane; Cell membrane; Cytoplasmic vesicle, autophagosome
Subcellular location (Human Protein Atlas): Plasma membrane; Cytosol
Gene Ontology:
Molecular function: protein binding; cholesterol binding; cholesterol transfer activity
Biological process: intracellular cholesterol transport; intracellular sterol transport
Cellular component: endoplasmic reticulum membrane; organelle membrane contact site; plasma membrane; endoplasmic reticulum-plasma membrane contact site; autophagosome
Genetic constraint (gnomAD): Loss-of-function variants: 47 observed, 77.02 expected, observed/expected ratio (o/e) 0.61, 90% interval 0.48 to 0.78. The upper end of that interval is the gene's LOEUF score, 0.78, which puts it in group 3 of 6, group 1 being the genes least tolerant of losing a copy. Missense variants: 742 observed, 901.23 expected, observed/expected ratio (o/e) 0.82, 90% interval 0.77 to 0.88. Synonymous variants: 375 observed, 380 expected, observed/expected ratio (o/e) 0.99, 90% interval 0.91 to 1.08.
Homologues: Orthologues: macaque GRAMD1A (98% identical), chimpanzee GRAMD1A (98% identical), dog GRAMD1A (96% identical), pig GRAMD1A (96% identical), guinea pig GRAMD1A (94% identical), mouse Gramd1a (93% identical), rat Gramd1a (93% identical), tropical clawed frog gramd1a (55% identical), zebrafish gramd1a (52% identical), Drosophila melanogaster GramD1B (32% identical), Caenorhabditis elegans ZC328.3 (21% identical). Paralogues in human: GRAMD1B (46% identical), GRAMD1C (35% identical), GRAMD2B (15% identical), GRAMD2A (12% identical).
Diseases named in the same sentence as GRAMD1A in open-access papers:
GRAMD1A is named in the same sentence as 19 diseases in open-access papers, as found by Europe PMC text mining. Sharing a sentence is not in itself a finding about the gene and the disease. The quoted sentences say what the papers report.
hepatocellular carcinoma (4 papers, 2016 to 2024). A malignant tumor that arises from hepatocytes. "In human cancers, GRAMD1A is currently only found to promote proliferation, migration, and invasion of hepatocellular carcinoma as well as the expansion of hepatocellular carcinoma stem cells." (PMID 35860689, 2022). "Meanwhile, upregulation of GRAMD1A expression promoted proliferation, migration, and invasion of hepatocellular carcinoma in in vitro assays." (PMID 35860689, 2022). "In addition, GRAMD1A was found to promote the expansion of hepatocellular carcinoma stem cells, the growth of hepatocellular carcinoma, and resistance to chemotherapy via STAT5." (PMID 35860689, 2022). "Moreover, GRAMD1A has been found to be involved in possible resistance to chemotherapy in patients with hepatocellular carcinoma." (PMID 35860689, 2022).
kidney cancer (2 papers, 2022 to 2023). Primary or metastatic malignant neoplasm involving the kidney. "GRAMD1A is related to immune infiltration in tumor microenvironments, and expression of GRAMD1A is significantly related to the survival of kidney cancer patients." (PMID 36999961, 2023). "The expression of GRAMD1A in kidney cancer cell lines and KIRC patients was analysed by quantitative polymerase chain reaction (qPCR)." (PMID 35860689, 2022). "High expression of GRAMD1A predicted poorer OS and relapse-free survival (RFS) for most cancers, including kidney cancer, cervical squamous cell carcinoma, liver cancer, and lung squamous carcinoma, especially in KIRC patients." (PMID 35860689, 2022).
Cirrhosis (1 paper, 2016). A chronic disorder of the liver in which liver tissue becomes scarred and is partially replaced by regenerative nodules and fibrotic tissue resulting in loss of liver function. "In contrast, GRAMD1A levels wasn’t associated with gender, age, clinical stage, TNM classification, cirrhosis or HbsAg." (PMID 27585821, 2016).
lung carcinoma (1 paper, 2022). "In the present study, we firstly found that GRAMD1A was highly expressed in a variety of cancer tissues by pan-cancer analysis, including kidney, breast, colon, bile duct, and lung cancers, among others." (PMID 35860689, 2022).
psoriasis (1 paper, 2022). An autoimmune condition characterized by red, well-delineated plaques with silvery scales that are usually on the extensor surfaces and scalp. "Besides, as one of the genes in the TLR7 regulatory pathway, GRAMD1A can be used to assess the response of psoriasis after treatment." (PMID 35860689, 2022).
renal carcinoma (1 paper, 2022). A carcinoma arising from the epithelium of the renal parenchyma or the renal pelvis. "Subsequently, the upregulation of GRAMD1A in KIRC was also validated in a number of renal cancer cell lines and in KIRC tissues from patients at our medical centre." (PMID 35860689, 2022).
renal clear cell carcinoma (1 paper, 2023). "The adverse impacts of GRAMD1A in renal clear cell carcinoma largely depend on the immunomodulatory effects of TILs in the tumor microenvironment, which can make it a biomarker for renal diseases." (PMID 38224029, 2023).
viral infections (1 paper, 2020). "Up-regulation of the cholesterol transporter GRAMD1A is interesting because this protein is required for the formation of autophagosomes, a key component of the autophagy pathway known to be involved in most viral infections." (PMID 32591346, 2020).
Wilms tumor (1 paper, 2024). An embryonal neoplasm characterized by the presence of epithelial, mesenchymal, and blastema components. "In summary, this study identified critical prognostic genes and molecular pathways associated with the progression of Wilms tumor, with GRAMD1A emerging as a key regulator." (PMID 39659787, 2024). "Although the role of GRAMD1A in tumorigenesis has been largely unexplored in other cancer types, our study is the first to demonstrate that elevated GRAMD1A expression is linked to poor overall survival (OS) and progression-free survival (PFS) in Wilms tumor (WT) patients." (PMID 39659787, 2024). "The identified prognostic genes, particularly GRAMD1A, SPR, EBAG9, RBM47, and RIDA, offer significant potential as both prognostic biomarkers and therapeutic targets for improving personalized treatment in Wilms tumor patients." (PMID 39659787, 2024).
tumor (9 papers, 2016 to 2025). "We used GSEA to analyze the association between GRAMD1A levels and tumor recurrence, and found patients with high GRAMD1A levels had high recurrence rate." (PMID 27585821, 2016). "To further validate the role of GRAMD1A in vivo, we established orthotopic xenograft models by injecting LOVO cells knocked-down or overexpressed GRAMD1A to observe the tumor growth and liver metastasis." (PMID 40707783, 2025). "Targeted inhibition of H3K9la or GRAMD1A suppressed the tumor growth in CRC patient-derived xenografts (PDX) models." (PMID 40707783, 2025). "In contrast, GRAMD1A knockdown group showed 20% (1/5) tumor formation and 0% (0/5) liver metastasis, compared to 80% (4/5) tumor formation and 0% (0/5) liver metastasis in scramble group." (PMID 40707783, 2025). "Our results showed that both LDH inhibitor and GRAMD1A inhibitor treatments significantly reduced tumor volumes and weight in CRC PDX models." (PMID 40707783, 2025). "Our results showed that GRAMD1A overexpressing group showed 100% (5/5) tumor formation and 80% (4/5) liver metastasis, compared to 80% (4/5) tumor formation and 0% (0/5) liver metastasis in vector group." (PMID 40707783, 2025). "Targeted inhibition of H3K9la or GRAMD1A reduced tumor growth in CRC patient-derived xenografts (PDX) models." (PMID 40707783, 2025). "External validation confirmed key hub genes, while functional assays in WT cell lines (WiT-49) assessed the role of GRAMD1A in tumor behavior." (PMID 39659787, 2024). "Specifically, GRAMD1A was significantly overexpressed in tumor tissues, while RIDA, RBM47, and SPR showed higher expression levels in normal kidney tissues." (PMID 39659787, 2024). "As overall survival is also affected by invasive and migration capabilities of the tumor, we analyzed migration of 786-O cells depleted of GRAMD1A, GRAMD1B and GRAMD1C using a wound-healing assay." (PMID 36270994, 2022). "Then we determined the role of GRAM1DA in the self-renewal of HCC stem cell and resistance to chemotherapy by overexpressing GRAMD1A, and the role of GRAMD1A in tumor growth by overexpressing or downregulating GRAMD1A." (PMID 27585821, 2016). "Soft agar growth ability assay found downregulation of STAT5 significantly inhibited anchorage-independent growth, suggesting GRAMD1A regulates tumor growth through regulating STAT5." (PMID 27585821, 2016). "While knockdown of GRAMD1A suppressed tumor growth, the tumor volume was smaller than Scramble control." (PMID 27585821, 2016). "In addition, subcutaneous xenograft tumor models using DLD1 cells harboring mutant (G13D/−), wild-type (+/–) or both KRAS alleles (G13D/+) further indicated that GRAMD1A knock-down showed more pronounced effect on tumor volume and weight in KRAS mutant tumors." (PMID 40707783, 2025). "Additionally, GRAMD1A overexpressing group showed significantly higher tumor volumes and liver metastasis numbers in H&E staining than the vector group, while GRAMD1A knockdown group had significantly lower tumor volumes compared to scramble group." (PMID 40707783, 2025). "Moreover, our subcutaneous xenograft tumor models using HCT116 cells also revealed that GRAMD1A knockdown reduced tumor volumes and weight in vivo." (PMID 40707783, 2025). "To further analyse the relationship between GRAMD1A with the immunity, we used the Kaplan-Meier plotter to compare the effect of GRAMD1A on OS in KIRC patients in enriched and deficient states of immune-infiltrating lymphocytes in the tumour microenvironment (TME)." (PMID 35860689, 2022). "In addition, the Sangerbox website, Kaplan-Meier plotter database, and TISIDB and TIMER databases were used to further analyse the correlation of GRAMD1A with microsatellite instability (MSI), tumour mutational burden (TMB), immune checkpoint genes, and tumour-infiltrating lymphocytes (TILs)." (PMID 35860689, 2022).
tumor (continued). "GRAMD1A, which facilitates lipid transfer between the mitochondria and the ER, similar to ORP5, promotes HCC self-renewal, tumor growth, and resistance to chemotherapy." (PMID 35386193, 2022). "We found GRAMD1A overexpression promoted the self-renewal of HCC stem cells, the resistance to chemotherapy and tumor growth." (PMID 27585821, 2016). "We found knockdown of STAT5 in Huh-7 and HepG2 with GRAMD1A overexpression suppressed the self-renewal of HCC stem cells, resistance to chemotherapy and tumor growth, suggesting STAT5 was an oncogene." (PMID 27585821, 2016). "In summary, we provide evidences that GRAMD1A is a prognostic factor, it promotes the self-renewal of HCC stem cells, resistance to chemotherapy and tumor growth through regulating STAT5." (PMID 27585821, 2016). "The molecular mechanisms by which GRAMD1A contributes to tumor progression are not fully elucidated, underscoring the need for further mechanistic exploration." (PMID 39659787, 2024). "Furthermore, while GRAMD1C expression was decreased in advanced-stage tumors, the expression of GRAMD1A and GRAMD1B showed an opposite pattern, with increased expression in late-stage tumor samples compared to early-stage tumor samples." (PMID 36270994, 2022). "We injected subcutaneously different number of cells into the flank of nude mice, and found overexpression of GRAMD1A promoted tumor growth, the tumor volume was larger than negative control." (PMID 27585821, 2016). "Functional analyses revealed GRAMD1A contributed to the self-renewal of HCC stem cells, resistance to chemotherapy and tumor growth of HCC determined by hepatosphere formation assay, side population (SP) analysis, TUNEL assay, soft agar growth ability assay and tumor growth model in vivo." (PMID 27585821, 2016). "Inhibition of STAT5 in indicated HCC cells overexpressing GRAMD1A suppressed the effects of GRAMD1A on the self-renewal of HCC stem cell, resistance to chemotherapy and tumor growth, suggesting GRAMD1A promoted the self-renewal of HCC stem cells and the development of HCC by increasing STAT5 level." (PMID 27585821, 2016). "Meanwhile, we found low GRAMD1A levels correlated with repressed self-renewal of HCC stem cell, suggesting GRAMD1A might regulate the tumor growth, drug resistance and the expansion of HCC stem cells." (PMID 27585821, 2016).
cancer (4 papers, 2022 to 2025). A tumor composed of atypical neoplastic, often pleomorphic cells that invade other tissues. "GRAM structural domain-containing protein 1A (GRAMD1A) is upregulated in a variety of human cancer tissues and is closely associated with tumourigenesis and progression." (PMID 35860689, 2022). "In this study, we used radar plots to clearly demonstrate the association of GRAMDIA with MSI and TMB in human cancers, and as expected, GRAMD1A was positively correlated with both MSI and TMB in KIRC." (PMID 35860689, 2022). "Combined KEGG analysis of metabolomic and RNA-seq results further validated that steroid biosynthesis and cancer related pathways were enriched in GRAMD1A-overexpressing cells." (PMID 40707783, 2025). "GRAMD1A is found to be expressed in a variety of human cancer tissues, including the digestive, urinary, and reproductive systems." (PMID 35860689, 2022). "GRAMD1A is widely expressed in the nucleus and cytoplasm of embryonic stem cells, cancer cell lines, and ectodermal, mesodermal, and endodermal tissues, and its function has not been fully explored." (PMID 35860689, 2022). "We used the Kaplan-Meier plotter database to explore the impact of GRAMD1A on the prognosis of a variety of human cancers." (PMID 35860689, 2022). "We also assessed the impact of GRAMD1A on the prognosis of human cancers by Kaplan-Meier analysis and forest plots, and for most cancers, upregulation of GRAMD1A expression was an unfavourable prognostic factor, a feature that was most prominent in KIRC patients." (PMID 35860689, 2022). "A pan-cancer analysis of GRAMD1A was performed on the Sangerbox website, and results showed that GRAMD1A was highly expressed in a variety of cancers, involving the respiratory, digestive, and urinary systems, with the greatest difference in the urinary system between KIRC and matched normal tissue." (PMID 35860689, 2022). "Given that immunotherapy has become a first-line treatment option for a wide range of solid tumours, we have analysed the relationship between GRAMD1A with MSI and TMB in human cancer through Sangerbox website tools." (PMID 35860689, 2022).
GRAMD1A also shares sentences with these, for which no sentence is quoted: liver cancer (2 papers); cervical squamous cell carcinoma (1); colorectal cancer (1); epilepsy (1); lymph node metastasis (1); Parkinson’s (1); renal diseases (1); Sepsis (1).